INSR (insulin receptor)
Diseases named in the same sentence as INSR in open-access papers (continued):
Sharing a sentence is not in itself a finding about the gene and the disease.
Hyperinsulinemia (continued). "In conclusion, we present support for a mechanism by which hyperinsulinemia impairs insulin receptor internalization into brain endothelial cells, thereby altering the regulation of molecular targets involved in cerebral blood flow." (PMID 37834116, 2023). "We previously reported that hyperinsulinemia alters insulin receptor presentation and reduces downstream insulin signaling in MBECs." (PMID 37834116, 2023). "Our observed data correlate with earlier research that reported a decrease in INSR tyrosine kinase activity and an elevation in total INSR protein level in a model of high-fat-diet induced hyperinsulinemia." (PMID 37697311, 2023). "We conclude that hyperinsulinemia alters the phosphorylation of molecular targets involved in clathrin-mediated endocytosis, disrupts signaling through the insulin receptor, and hinders the capacity for blood flow regulation by brain endothelial cells." (PMID 37834116, 2023). "For example, reduced AKT and ERK signaling and INSR abundance were also reported in hyperinsulinemia‐treated β‐cells (INS1E cell line and rat islets) and enteroendocrine L cells." (PMID 34921686, 2022). "Consistent with the reduction in Insr mRNA, total INSR protein abundance was robustly decreased in both 2 and 200 nM hyperinsulinemia groups in an insulin dose‐dependent manner." (PMID 34921686, 2022). "The fraction of INSR internalized during acute insulin signaling seemed to be recalibrated instead of drastically affected by hyperinsulinemia under these conditions." (PMID 34921686, 2022). "Before starvation, both hyperinsulinemia groups had increased INSR phosphorylation, suggesting that there was continuous insulin signaling during the high insulin treatments." (PMID 34921686, 2022). "Using fluorescence microscopy, immunoblotting, and gene expression, we tested senescence markers in human hepatocytes subjected to chronic hyperinsulinemia in vitro and validated the data in vivo by using liver-specific insulin receptor knockout (LIRKO) mice." (PMID 35872305, 2022). "This intrinsic defect in insulin receptor signaling in PCOS usually leads to hyperinsulinemia as observed in the present results with elevated levels of plasma insulin in PCOS animals compared with the control." (PMID 36071485, 2022). "To further examine the direct effects of hyperinsulinemia on the proximal stages of insulin signaling, we examined INSR abundance, phosphorylation and internalization in cultured muscle cells." (PMID 34921686, 2022). "This resultant hyperinsulinemia can lead to resistance to insulin through insulin receptor downregulation." (PMID 35836436, 2022). "Consistently, we observed that hyperinsulinemia led to a substantial reduction in Insr gene expression, and subsequently a reduced surface INSR and total INSR protein, both in vitro and in vivo." (PMID 34921686, 2022). "The only increased DPP in both the liver and skeletal muscle of ob/ob mice was the beta subunit of the insulin receptor (Irβ), which is consistent with the hyperinsulinemia observed in ob/ob mice." (PMID 33748705, 2021). "The present work investigates the molecular mechanisms of high carbohydrate and fat diet in inducing prediabetic hyperinsulinemia and effect of exercise on InsR signaling events, muscular AChE, and lactate dehydrogenase activity." (PMID 33708999, 2021). "One of them has been the deficient model of the insulin receptor in the liver specifically (LIRKO), which is characterized by alterations in glucose metabolism, together with compensatory hyperinsulinemia." (PMID 34440804, 2021). "Given the significant saturation of clearance with hyperinsulinemia, the involvement of the insulin receptor seemed likely." (PMID 33466380, 2021). "Similar to the findings presented here in Huh7 cells, direct downregulation of INSR by miR-27b has also been previously shown in chronic hyperinsulinemia-induced IR adipocytes." (PMID 33212990, 2020).
Hyperinsulinemia (continued). "Preclinical studies have found that hyperinsulinemia promotes the growth and metastasis of breast cancers by activating the insulin receptor (IR)/insulin-like growth factor 1 receptor (IGF-1R) signaling pathways." (PMID 32393319, 2020). "Subsequently, hyperinsulinemia can lead to resistance to insulin through insulin receptor down-regulation." (PMID 33003490, 2020). "The endocytosis and/or recycling process of INSR are slowed down leading to hyperinsulinemia with altered insulin response and insulin clearance." (PMID 31658625, 2019). "Impairment of clathrin-dependent INSR endocytosis has been identified in the hepatocytes from hyperinsulinemia mice." (PMID 31658625, 2019). "The insulin receptor (IR) mediates both metabolic and mitogenic effects especially when overexpressed or in clinical conditions with compensatory hyperinsulinemia, due to the metabolic pathway resistance, as obesity diabetes." (PMID 30453495, 2018). "ZIP14 seem to affect glucose metabolism as Zip14 knockout mice display hyperinsulinemia, augmented insulin receptor phosphorylation, and increased liver glucose." (PMID 28303117, 2017). "Of note, hyperinsulinemia increases mammary tumor growth in vivo, and blockade of the INSR/IGF1R reduces tumor growth in hyperinsulinemic mice." (PMID 28038446, 2017). "AD patients had reduced brain insulin receptor (IR) activity, lower CSF insulin levels and peripheral blood hyperinsulinemia and an attenuated expression of IR and IGF receptors." (PMID 27240327, 2016). "Given evidence showing prostate cancer responsiveness to insulin in mouse models and insulin receptor expression by human prostate cancer cells, it is possible that hyperinsulinemia facilitates progression to castration-resistant prostate cancer (CRPC)." (PMID 27599544, 2016). "The diagnosis of type B insulin resistance syndrome is based on the presence of hyperglycemia (sometimes hypoglycemia paradoxically), hyperinsulinemia and positive insulin receptor antibodies." (PMID 27142369, 2016). "For instance, due to the homology between IGF-1R and INSR, the inhibition of IGF-1R signaling disrupts INSR signaling and results in unwanted side effects, such as hyperglycemia and hyperinsulinemia." (PMID 24816813, 2014). "One contributor to reduced insulin signaling is a downregulation of insulin receptor expression induced by hyperinsulinemia." (PMID 24252636, 2013). "Animals double-heterozygous for the insulin receptor and Timp3 developed spontaneous mild hyperglycemia and hyperinsulinemia at three months, and overt glucose intolerance and hyperinsulinemia at six months." (PMID 21980496, 2011). "Another potential mechanism linking schizophrenia and long-term hyperinsulinemia is dysregulation of insulin-receptor-mediated signaling, which has a role in learning and memory as well as in regionally specific glucose metabolism in the brain." (PMID 21429189, 2011). "In an attempt to keep euglycemia, insulin secretion increases and the resultant compensatory hyperinsulinemia, in obese patients, reduces the expression of the membrane insulin receptor (down regulation), which generates more resistance to the insulin action." (PMID 15963228, 2005). "This concept also applies to hyperinsulinemia and the insulin receptor." (PMID 41009753, 2025). "Hyperinsulinemia can result from both reduced insulin uptake due to decreased insulin receptor levels and attenuation of insulin signaling pathway by modification the intermediate signaling molecules like the insulin receptor substrates." (PMID 40643485, 2025). "It has been hypothesized that INSR hypoglycosylation during the fetal period may trigger compensatory hyperinsulinemia in utero, potentially persisting after birth and contributing to neonatal hyperinsulinemic hypoglycemia." (PMID 40771275, 2025). "Recent results indicate that hyperinsulinemia reduces insulin receptor gene expression in muscle." (PMID 38201980, 2024).
Hyperinsulinemia (continued). "Similarly, another study found that IRKO+/− mice, which exhibit hyperinsulinemia due to insulin receptor gene knockout, show an extended lifespan." (PMID 39872311, 2024). "The karyokinetic effect of insulin could be attributed to direct interactions with insulin receptors (IR) on (pre)neoplastic target cells, or it may result from changes in endogenous hormone metabolism due to hyperinsulinemia." (PMID 38786750, 2024). "Proper insulin signaling relies on the regulated internalization of insulin bound to the insulin receptor, a process which is disrupted by hyperinsulinemia via an unknown mechanism." (PMID 37834116, 2023). "Thus, the goal of this study was to characterize the impact of hyperinsulinemia on the regulation of molecular targets involved in cerebral blood flow and insulin receptor internalization into brain endothelial cells." (PMID 37834116, 2023). "Our results demonstrate that inhibition of clathrin-mediated endocytosis did not alter internalization in hyperinsulinemic cells as in naïve cells, suggesting that hyperinsulinemia reduces the role of clathrin in insulin receptor uptake into brain endothelial cells." (PMID 37834116, 2023). "As demonstrated, hyperinsulinemia worsens insulin receptor internalization into MBECs." (PMID 37834116, 2023). "Moreover, a recent preprint demonstrates that hyperinsulinemia decreases insulin receptor (Insr) transcription in muscle." (PMID 34823065, 2022). "Therefore, basal surface INSR, as well as dose‐ and time‐dependent INSR internalization were examined in our hyperinsulinemia model using a surface biotinylation assay." (PMID 34921686, 2022). "The proposal mechanism for this association was the activation of insulin and insulin-like growth factor pathway, which share affinity with insulin receptor and that could be over activated by compensatory hyperinsulinemia to insulin resistance." (PMID 35782938, 2022). "Insulin receptor substrate proteins are generally considered to be the node in the insulin signaling system that is critically involved in the development of insulin insensitivity during metabolic stress, hyperinsulinemia, and inflammation." (PMID 33810179, 2021). "Chronic sustained hyperinsulinemia, INSRs, IGF1Rs, and INSR/IGF1R hybrids, in addition to chronic inflammation, ncRNAs, and microbiota have been proposed as factors that may play a role in all tumor stages." (PMID 34681797, 2021). "Defects in the expression and/or activity of the insulin receptor might contribute to hyperinsulinemia in women with PCOS." (PMID 34484117, 2021). "It has also been reported that hyperinsulinemia could activate the insulin receptor (IR)/insulin-like growth factor 1 receptor (IGF-1R) signaling pathway to promote the development of breast cancer." (PMID 34434893, 2021). "Insulin powerfully inhibits ketogenesis, therefore insulin receptor insensitivity and hyperinsulinemia could delay keto-adaptation." (PMID 32369441, 2020). "Insulin is an anabolic hormone, and interaction with the cardiac insulin receptor as observed in congenital hyperinsulinism and in infants of diabetic mothers might explain the large weight and plethoric aspect of these patients." (PMID 31840185, 2020). "Quantification of diet‐induced pTyr in liver‐specific insulin receptor knockout animals (LIRKO) demonstrated that only a subset of these phosphorylation changes could be attributed to hyperinsulinemia and persistent insulin receptor signaling." (PMID 31464373, 2019). "It is reasonable to assume that in an early hyperinsulinemia state such as prediabetes, symptoms are caused by a pseudo-insulin resistance state by impaired INSR trafficking rather than a genuine insensitivity of INSR signaling." (PMID 31658625, 2019). "Given the paramount importance of insulin receptor and compensatory hyperinsulinemia in the induction of androgen excess in PCOS women, LCD may also improve hyperandrogenism-related symptoms." (PMID 31885557, 2019).
Hyperinsulinemia (continued). "Insulin resistance and consequent hyperinsulinemia can directly induce carcinogenesis through the insulin receptor or indirectly, when there is an increase in the levels of insulin growth factors (IGFs), sex steroid hormones, and inflammatory processes, among others." (PMID 31284513, 2019). "Moreover, the reduction of macrophage Irs2 expression is mediated by hyperinsulinemia via the insulin receptor (IR)." (PMID 30451856, 2018). "Previously, tissue-specific knockouts of glucose transporter (GLUT) 4 in muscle exhibited severely impaired glucose tolerance and hyperinsulinemia, and mice with a knockout of the insulin receptor in muscle revealed increased triglycerides and free fatty acids." (PMID 29402279, 2018). "Mice with liver-specific inactivation (L-SACC1) or with global null mutation of Ceacam1 (Cc1−/−) exhibit impairment in insulin clearance leading to chronic hyperinsulinemia and systemic insulin resistance (owing to downregulation of insulin receptor expression)." (PMID 28184213, 2017). "Blocking the effects of hyperinsulinemia in ob/ob mice by knocking down the insulin receptor further induced FMO3 protein, consistent with the notion that the signaling pathways utilized by insulin to suppress Fmo3 become partially resistant to insulin in ob/ob mice." (PMID 25849138, 2015). "Some cancer cells have increased insulin receptor (IR) content, and in the setting of hyperinsulinemia, certain tumors may demonstrate increased activation of IR signaling pathways." (PMID 25114970, 2014). "This beneficial effect of p110α inactivation derives in part from a suppressed down-regulation of insulin receptor substrate (IRS) protein levels induced by age-related hyperinsulinemia, and correlates with enhanced insulin-induced Akt signalling in aged p110α-deficient mice." (PMID 23483710, 2013). "In addition, hyperinsulinemia can activate the INSR/IRS/PI3K/Akt/mTOR signaling pathway, promoting inhibition of lipolysis and enhancement of lipogenesis in adipocytes, while lipid metabolism disorders remain the core driving factor for lipid accumulation in atherosclerosis." (PMID 41377946, 2025). "In addition, leptin therapy may affect insulin receptor substrates, such as insulin-2, directly or indirectly by reducing endogenous hyperinsulinemia." (PMID 38957655, 2024). "Leaky intestinal could promote LPS leakage into blood circulation, and results in immune system response that impairs with insulin receptor function, resulting in IR, and finally IR/Hyperinsulinemia may stimulate testosterone release, interfering with follicular growth." (PMID 37968684, 2023). "Thus, the interplay among hyperinsulinemia, insulin receptor resistance, downregulation of insulin-like growth factor-1 receptor, and IR signaling pathways could explain the molecular basis of the brain IR state." (PMID 37891752, 2023). "However, when the situation persists and consolidates, in the presence of concomitant disturbing factors such as oxidative stress and systemic inflammation, hyperinsulinemia leads to a progressive defect of the insulin receptor (INSR) and of downstream signal transduction systems involved in IR." (PMID 37298967, 2023). "However, impairments of the hepatic insulin receptor may be equally important in producing systemic insulin resistance and hyperinsulinemia." (PMID 34766133, 2021). "Thus, one may speculate that up-regulation of insulin receptor isoforms is a compensatory consequence to the model-induced hyperinsulinemia, and/or to the inactivated tyrosine kinase, which in turn impedes the proper autophosphorylation post-receptor cascades." (PMID 22649556, 2012). "We found that hyperinsulinemia promoted hypothalamic neuronal IGF1 resistance, evidenced by reduced INSR and IGF1R protein levels in immortalized hypothalamic neurons, primary hypothalamic cultures, and human iPSC-derived hypothalamic neurons." (PMID 40105689, 2025).
Hyperinsulinemia (continued). "It is worth noting that CREB3 probably suppresses INSR signaling by binding to intracellular domain of INSR‐A and INSR‐B, which provides novel insight for therapy of HCC patients with hyperinsulinemia." (PMID 38952575, 2024). "The influence of insulin on breast cancer is mainly based on the effect of IR or hyperinsulinemia, which activates the extracellular-related-kinase cascade and the AKT pathway through activation of the insulin receptor or the IGF receptor in breast cancer." (PMID 38904041, 2024). "In immunocompetent patients, the occurrence of hyperinsulinemia serves to enhance the innate immune response and enhance the antiviral effector response of CD8 T cells, as insulin receptor and CD28 signaling converge on PI3K." (PMID 37718435, 2023). "Hyperinsulinemia, a salient EMS is known to trigger IR by dampening INSR autophosphorylation events, leading to a short-circuit in downstream signal transmission." (PMID 37697311, 2023). "Global RNA‐sequencing of cells both before and after nutrient withdrawal highlighted genes in the insulin receptor (INSR) signaling, FOXO signaling, and glucose metabolism pathways indicative of ‘hyperinsulinemia’ and ‘starvation’ programs." (PMID 34921686, 2022). "We demonstrated that in vitro hyperinsulinemia and serum ‘fasting’ have profound effects on AKT and ERK signaling, INSR abundance and localization, and transcriptional activities." (PMID 34921686, 2022). "In the present study, metformin significantly increased INSR expression in PCOS-IR F1 rats, possibly contributing to improved hyperinsulinemia and IR, thus reducing PCOS-IR incidence in the F1 female rats." (PMID 34484117, 2021). "The presence of hyperinsulinemia in women with PCOS-IR has been reported before, possibly due to some defects downstream of the insulin receptor." (PMID 34484117, 2021). "In infants of diabetic mothers and congenital hyperinsulinism, the CHCG is presumably due to the interaction of insulin with the intact insulin receptor." (PMID 31840185, 2020). "Although hyperinsulinemia appears to increase INSRA expression, and the molecules that regulate alternative INSR splicing have been identified, the exact stimuli that effect changes in isoform ratio are unclear." (PMID 25742416, 2015). "Hyperinsulinemia stimulates the liver to produce more insulin-like growth factor (IGF), another mitogen and an anti-apoptotic agent which binds insulin receptor/IGF receptor and stimulates prostate growth." (PMID 24267821, 2013). "Thus, it cannot be excluded that the observed increase in Pomc-expressing neurons in adult L1 mice is merely a result of altered metabolism in L1 mice (e.g., glucose intolerance and hyperinsulinemia) rather than a direct consequence of hypothalamic InsR deficiency." (PMID 22319636, 2012). "Consistent with other models of chronic hyperinsulinemia, IDE-KO mice exhibited reductions in insulin receptor (IR) levels and/or function in multiple tissues that, like the diabetic phenotype itself, emerged in an age-dependent manner." (PMID 21695259, 2011). "In the case we presented, the absence of hypoglycemic attacks and hyperinsulinemia, and negative INSR antibodies allowed us to eliminate type B IRS." (PMID 40696585, 2025). "Thus, in the pathological condition of hyperinsulinemia, insulin mainly stimulates HCC progression through interaction with INSR." (PMID 38952575, 2024). "The promotion of hepatocyte senescence by hyperinsulinemia is absent in mice with a liver-specific knockout of the insulin receptor whereas enhanced senescence was still occurring in white adipose tissue." (PMID 37854186, 2023). "Second, acute insulin stimulation following hyperinsulinemia reduces, but does not eliminate, insulin receptor activity." (PMID 37834116, 2023). "Together, these data suggest that hyperinsulinemia impairs clathrin-mediated insulin receptor endocytosis, an event that is not rescued by caveolin-mediated mechanisms." (PMID 37834116, 2023).